KIF2C (kinesin family member 2C)
Diseases named in the same sentence as KIF2C in open-access papers (continued):
Sharing a sentence is not in itself a finding about the gene and the disease.
tumor (continued). "These suggest that KIF2C might be involved in tumor progression and be a potential prognostic factor in LUSC." (PMID 32411535, 2020). "Kinesin family member 2C (KIF2C) has been served as a modulator in bipolar spindle formation, microtubule depolymerization, and chromosome segregation, and it could promote the tumor proliferation and metastasis." (PMID 32411535, 2020). "Because KIF-2C is expressed highly in healthy testis, we reasoned that the association between prognosis and the levels of KIF-2C in tumor tissues might differ between male and female patients with ESCC." (PMID 27563815, 2016). "In addition, overexpression of KIF2C could lead to chromosomal aberrations that promote tumor progression." (PMID 40433108, 2025). "Indeed, the tumor promoting effects could be abrogated by KIF2C-silencing and restored by addition of exogenous PAF, indicating a possible regulatory role of KIF2C in MEK/ERK signaling transduction." (PMID 38433242, 2024). "In addition, KIF2C participates in cytoskeleton remodeling during tumor metastasis." (PMID 37717078, 2023). "In addition, KIF2C has been identified in cytoskeletal remodeling during tumor metastasis." (PMID 37717078, 2023). "However, KIF2C expression was downregulated in tumor tissues (e.g., TCGT, LAML)." (PMID 35153749, 2021). "Similarly, the CD8+ T cell expression level is positively correlated with the cumulative survival of EC, which suggested that KIF2C may be involved in remodeling the tumor immune environment and thereby promoting the malignant progression of EC." (PMID 34650608, 2021). "Additionally, KIF2C has been identified in cytoskeletal remodeling during tumor metastasis." (PMID 34650608, 2021). "Further analysis revealed that high levels of KIF2C expression were significantly associated with tumor differentiation, recurrence, and a poorer prognosis in HCC patients, suggesting that the upregulated expression of KIF2C in HCC may play a role in malignancy." (PMID 32748349, 2021). "Functional silencing of KIF2C led to decreased proliferation and invasive capacity of LUAD cells, supporting its potential role as a tumor-promoting factor." (PMID 41341805, 2025). "Western blot analysis substantiated these findings at the protein level, revealing significantly elevated expression of CCNA2, CSRP2, ILF2, KIF2C, RACGAP1, and VARS in HCC tissues versus adjacent non-tumor tissues." (PMID 41323394, 2025). "Western blotting revealed significantly elevated levels of CCNA2, CSRP2, ILF2, KIF2C, RACGAP1, and VARS proteins in HCC tissues compared to adjacent non-tumor tissues." (PMID 41323394, 2025). "The expression levels of KIF2C, CENPA, CDC20, UBE2C, ESPL1, KIF23, and PLK1 were significantly higher in the tumor tissues of patients with a HOST-response compared to those without a HOST-response." (PMID 39201599, 2024). "Recent progress in establishing patient-derived tumor organoids (PDO) and stroma organoids in combination with CRISPR technologies provide novel tools to study the molecular regulatory network of KIF2C deregulation in elaborated in vivo models." (PMID 38344808, 2024). "Additionally, the precise regulation of KIF2C not only ensures the normal physiological process of cell mitosis but also interferes with the function of KIF2C, which may defect mitosis and make the structure of the chromosome unstable, both signs of tumor progression." (PMID 36900292, 2023). "It is worth noting that there is sufficient evidence to indicate that the expression of KIF2C is abnormal in PDAC and plays a role in tumor progression." (PMID 36900292, 2023). "First, we found an increased number of tumor infiltrating immune cells, including T cells, CD8 + T cells, cytotoxic lymphocytes, monocytic lineage, and neutrophils in the high KIF2C expression group compared with the low expression group." (PMID 37016301, 2023).
tumor (continued). "The most significant target genes were putative tumor oncogenes/promoters (TK1, KIF2C, UBE2C, AURKB) and potential tumor suppressors (CALCOCO1, CIRBP, KLHDC1, CBX7)." (PMID 36358602, 2022). "Our findings also revealed significant correlations between KPNA2, LPCAT1, KIF2C, and SPP2 expression and three clinical traits, including ECOG (p < 0.01), vascular tumour cell type (p < 0.05), and tumour status (p < 0.05)." (PMID 35915607, 2022). "In order to elucidate the effect of TBX15 on miR-152, KIF2C and PKM2 expression in vivo, we established tumor xenografts by implanting MCF7/ADR cells stably expressing TBX15." (PMID 34663310, 2021). "The results showed that the mRNA expression levels of hub genes (PBK, KIF2C, NUF2, KIF20A, RAD51AP1 and DEPDC1) in tumor samples (EAC, ESCC) were significantly higher than in normal samples (P < 0.05)." (PMID 33403046, 2021). "A xenograft tumor model was established to further explore the role of the TBC1D7 and KIF2C interaction in tumor growth." (PMID 32748349, 2021). "In this research, we further assessed the differential expression of five hub genes (TPX2, KIF2C, CDCA8, BUB1B, and CCNA2) in various clinical stages, and the results showed that their expression was significantly increased in advanced tumour stages." (PMID 31285741, 2019). "Validation using clinical samples from Tianjin Chest Hospital confirmed that KIF2C expression levels were significantly higher in tumor tissues compared with matched adjacent non-cancerous tissues, as determined by quantitative PCR." (PMID 41341805, 2025). "Among the top 100 genes that have similar expression patterns of KIFC1 in the tumors of the TCGA cohort, the KIFC1 expression was significantly and positively correlated with KIF2C, NCAPH, KIF4A, TPX2, and CDCA5 expression in all of the tumor types in the TCGA database." (PMID 35327439, 2022). "Some scientists found that KIF2C was highly expressed in HCC, correlating with tumor malignancy." (PMID 36072970, 2022). "To further investigate whether KIF2C can also promote HCC cell proliferation in vivo, we established a xenograft tumor model by subcutaneously injecting the indicated HCC cells into nude mice." (PMID 32748349, 2021). "We found that the expression of KIF2C was dependent on the tumor types, whereas it had no direct correlation with tumor stage, lymph node invasion, and distant metastasis." (PMID 35153749, 2021). "Previous studies have shown that TMB and MSI-H are predictive biomarkers for tumor immunotherapy TMB and MSI-H have previously been demonstrated to be predictive biomarkers for tumor immunotherapy, thus we analyzed the correlation between KIF2C expression and different tumor TMB, MSI and MMRs." (PMID 35685442, 2022). "The protein expressions of most of these genes were higher in UCEC tissues compared to non-tumor tissues, according to the Human Protein Atlas database, except that no protein expression was detected for KIF2C gene and there was no expression data for BUB1 gene in this database." (PMID 34868993, 2021). "Indeed, the detailed mechanism that KIF-2C promotes tumor progression in male ESCC patients has not been revealed." (PMID 27563815, 2016). "This led to the selection of seven antigens found to be overexpressed in both mouse MM tumor lines under investigation and that were nearly absent in all other mouse normal tissues: KIF20A, KIF2C, MMP9, MNDA, OLFML2B, TROAP, and ULBP1." (PMID 31428586, 2019).
infection (3 papers, 2021 to 2024). The state of being infected such as from the introduction of a foreign agent such as serum, vaccine, antigenic substance or organism. "An increase in productive infection was detected after knockdown of FLNA, HMGB3, PTBP1, HSP90AA1, and KIF2C (green bars)." (PMID 34194479, 2021).
blood cancer (1 paper, 2021). "For blood cancer, KIF2C presented the opposite manner in OS (HR = 0.53, COX p = 0.017) and DSS (HR = 2.53, COX p = 0.000363)." (PMID 35153749, 2021).
KIF2C also shares sentences with these, for which no sentence is quoted: nasopharyngeal carcinoma (4 papers); breast tumors (3); colon cancer (3); lung squamous cell carcinoma (2); malaria (2); myocarditis (2); adenocarcinoma (1); bladder urothelial carcinoma (1); brain glioma (1); calcinosis (1); Cerebral ischemia (1); cervical squamous cell carcinoma (1); Cervical Tumor (1); clear cell renal cell carcinoma (1); gastric tumours (1); head and neck squamous cell carcinoma (1); invasive ductal carcinoma (1); Klinefelter syndrome (1); metastasis (1); neuroblastoma (1); neuropathies (1); nevus (1); oligospermia (1); pancreatic ductal adenocarcinoma (1); paraganglioma (1); pheochromocytoma (1); psoriasis (1); psychiatric disorder (1); rheumatoid arthritis (1); schizophrenia (1).
A further 5 diseases each share a sentence with KIF2C in 1 paper.